PIK3R1 (phosphoinositide-3-kinase regulatory subunit 1)
Diseases named in the same sentence as PIK3R1 in open-access papers (continued):
Sharing a sentence is not in itself a finding about the gene and the disease.
tumor (continued). "In the WES samples, we detected somatic mutations in known PCa genes, including KMT2D, MTOR, SPOP, and PIK3R1, indicating tumor content in tissues assessed by single-cell analysis." (PMID 35013146, 2022). "Phosphoinositide-3-Kinase Regulatory Subunit 1 (PIK3R1) is believed to function as a tumor suppressor, while Phosphoinositide-3-Kinase Regulatory Subunit 2 (PIK3R2) as a tumor driver." (PMID 35395865, 2022). "Molecular profiling of her tumor demonstrated the following genetic mutations: CREBBP Y1450 C, MLL2 Q1949 * and PIK3R1 Q329." (PMID 35267638, 2022). "PIK3R1, a tumor suppressor gene, belongs to PI3K pathway that is one of the most altered pathways in cancer." (PMID 33670375, 2021). "hsa-miR-486-5p inhibits tumor growth and improves chemotherapy sensitivity by targeting PIK3R1 (phosphoinositide-3-kinase regulatory subunit 1) and TWF1 (twinfilin actin binding protein 1), respectively." (PMID 35118066, 2021). "All these results support the notion that exosomal miR‐21‐5p derived from MSCs exerts tumour promoter properties in OS by down‐regulating PIK3R1 so as to activate the PI3K/Akt/mTOR signalling pathway." (PMID 34741385, 2021). "qRT-PCR revealed that knockdown of circ_0000215 repressed circ_0000215 and PIK3R1 expressions in tumor tissues, while increasing miR-512-5p expression." (PMID 34765599, 2021). "PIK3R1/p85α is abundant isoform in tumour‐free tissues, but its expression is reduced in tumour cells." (PMID 34741385, 2021). "The results of our study demonstrate that there were specific conserved sites between miR‐21‐5p and 3’‐UTR of PIK3R1, and PIK3R1 down‐regulation by MSC‐derived exosomes containing abundant miR‐21‐5p exerts tumour promoter properties in OS." (PMID 34741385, 2021). "Differential methylation of the ITGA4, SFN, ITGA2, and PIK3R1 genes allowed the discrimination between normal and tumour tissue and correlated with patient survival." (PMID 34944974, 2021). "It has been reported that PIK3R1 is differentially expressed in many human cancers and is closely related to tumor progression and metastasis, which make it an important therapeutic target through inhibiting the PI3K/AKT/mTOR pathway." (PMID 33192484, 2020). "For example, PIK3R1 functions as a tumor suppressor in hepatocellular carcinomas and renal cancer, whereas acts as an oncogene in ovarian and colon tumors and plays a role in tumor progression and metastasis." (PMID 31938022, 2020). "The copy-number stable tumor contained multiple mutations affecting key genes in the PI3K pathway, such as PTEN, FGFR2 and two deleterious mutations in the PIK3R1 gene." (PMID 32873813, 2020). "These genes included those that have been reported to be associated with the biological behaviour of tumour cells (NTRK2, MAPK8, BCOR, and PIK3R1 genes)." (PMID 31034520, 2019). "Significantly, the tumor burden of PIK3R1 shRNA tumors was higher than that of tumors expressing vector control, indicating that PIK3R1 downregulation enhances tumorigenesis and metastatic dissemination." (PMID 30755611, 2019). "Western blotting confirmed that the PIK3R1-shRNA tumor nodules maintained decreased levels of p85α and increased levels of STAT3 and AKT phosphorylation." (PMID 30755611, 2019). "The PIK3R1 gene product is a protein kinase regulator with expected molecular weight of 84kDa known to be involved in tumor cell migration and invasion." (PMID 31100936, 2019). "The target genes of miR-486 included PIK3R1, one of the oncogenes that promotes cell proliferation and tumour cell invasion." (PMID 31034520, 2019).
tumor (continued). "The PIK3R1 gene was confirmed to be a direct target of miR-486-5p by dual-luciferase reporter assay, and the expression level of miR-486-5p was inversely correlated with that of PIK3R1 in tumor tissues (r = −0.774, p < 0.01)." (PMID 31402930, 2019). "PIK3R1 mRNA expression is also significantly decreased in many of these tumor types, compared with the corresponding normal tissues." (PMID 30755611, 2019). "The PIK3R1 gene is known to play a tumor suppressor role because the PI3K subunit p85α (p85α) regulates and stabilizes p110α." (PMID 30126855, 2018). "In ESCCs, we identified amplification or mutation of EGFR in 19% of tumours and alterations of PIK3CA, PTEN or PIK3R1, all of which are believed to activate the PI3K pathway, in 24% of tumours." (PMID 28052061, 2017). "CNA driver genes such as PIK3CB lost in 9 tumours, PIK3R1 and AKT amplified in 6 and 4 tumours respectively are linked with 58, 57 and 53 KEGG pathways underlining the tremendous effects of individual gene losses and gains." (PMID 28486536, 2017). "The deletion rate of PIK3R1 in our samples was 4.3% (4/94) and the mRNA expression levels of this gene were significantly lower in tumours than in normal tissues (P=3.71 × 10−24, paired t-test)." (PMID 28548104, 2017). "Previous studies show that PIK3R1 suppresses tumor cell invasion and migration by reducing PI3K/AKT signaling." (PMID 28033431, 2016). "Overall, 45.2% of all tumours had a functional mutation in at least one member of the Akt signalling pathway (PIK3CA, AKT1, PIK3R1, PTEN and FOXO3)." (PMID 27161491, 2016). "We first tested the effect of PIK3R1 silencing on the growth of tumor xenografts derived from H226, H520, and CaLu-1 cells with p85β/p85α ratios >2." (PMID 27835880, 2016). "We discovered that the expression of PIK3R1 in RCC negatively correlated with tumor progression and metastasis." (PMID 25757764, 2015). "Consistent with the pathway analysis, PyMT tumours exhibit a major interaction hub that centres on the PI3K regulatory subunit Pik3r1." (PMID 25200860, 2014). "PTEN underexpression was significantly mutually exclusive with PIK3CA, PIK3R1 and AKT1 mutations (p = 0.00016), as it was observed in only one AKT1 mutated tumor and 14 PIK3CA mutated tumors." (PMID 24229379, 2013). "As PIK3CA and AKT1 are oncogenes activated by mutations and as PIK3R1 and PTEN are tumor suppressors mainly inactivated by underexpression, respectively, all these alterations result in PI3K pathway activation." (PMID 24229379, 2013). "PIK3R1 underexpression was found in 283 (61.8%) cases, indicating a relevant tumor alteration occurring in the majority of tumor samples." (PMID 24229379, 2013). "On the contrary, the PIK3R1 gene appears to play a tumor suppressor role because PI3K subunit p85α (p85α) regulates and stabilizes p110α." (PMID 24229379, 2013). "Although a target gene in this region is still to be identified, several candidates do exist (for example, PIK3R1 located on chromosome 5q13.1, previously found to be homozygously deleted in a BRCA1-mutated tumor)." (PMID 20576095, 2010). "Many human tumor samples also gained expression of a coordinately regulated module associated with advanced malignancy (ABCC1, FOXO3A, LIF, PIK3R1, PRNP, TNC, TIMP3 and VEGF)." (PMID 17615082, 2007). "Using qPCR that defines amplification as tumours with hTERT gene content greater than that of PIK3R1 (5q13.1), we found amplification in 57% of NSCLC." (PMID 16641908, 2006). "Stratified Fisher’s exact tests confirmed that the lower mutation frequencies in TA-UC (PIK3CA, combined P = 0.008; PIK3R1, combined P = 0.001) were not driven by the different distributions of tumor grades in our TA-UC and de novo UC cohorts." (PMID 40846762, 2025). "Overall, PIK3R1 mutations trigger a hyperactive PI3K/AKT pathway, leading to increased cellular proliferation, resistance to apoptosis, and enhanced migration and invasion, allowing metastasis and tumor cells to invade surrounding tissues." (PMID 40564017, 2025).
tumor (continued). "Collectively, these findings indicate that PIK3R1 functions as a tumor suppressor." (PMID 39850811, 2024). "Out of the six components identified as targeting PIK3R1, five originate from the Huangqi herb, with jaranol being the most critical component in the combined use of Danggui and Huangqi to enhance immunity and inhibit tumor growth by interacting with PIK3R1." (PMID 38863309, 2024). "PIK3R1 encodes the regulatory subunit (p85α) of the PI3K complex, and multiple studies have shown its expression is often reduced in human cancers, contributing to tumor development." (PMID 39850811, 2024). "The decrease of PIK3R1 is significantly correlated with tumor stage, metastasis and prognosis." (PMID 38533261, 2024). "Thus, the suchilactone/kaempferol combination activates the immune system and inhibits tumor growth by targeting PIK3R1, establishing its importance in the anti‐tumor effects of the combined therapy with Danggui and Huangqi." (PMID 38863309, 2024). "Additionally, PIK3R1 is upregulated in several cancers and is involved in tumor metastasis, chemotherapy resistance, and progression." (PMID 38184597, 2024). "Moreover, these tumor types have significantly lower level of PIK3R1 mRNA expression as compared to normal tissues." (PMID 37781028, 2023). "Moreover, these core genes (Pik3r1, Akt1, Myc, Egfr, Hif1a, Vegfr, Jun, and Stat3) are closely related to the tumor immune microenvironment, exclusively T cell immune function." (PMID 37799727, 2023). "The results showed that two of the ten patients (patients #3 and #6) displayed higher levels of isonicotinylation in tumour tissues than in the adjacent normal tissues, and the levels of PIK3R1 were increased concomitantly in tumour tissues of the same patients (patients #3 and #6)." (PMID 34545082, 2021). "We found that differential methylation of the ITGA4, SFN, ITGA2, PIK3CD, and PIK3R1 genes allowed the discrimination between normal and tumour tissue evidencing that all 12 CpGs identified were good to excellent diagnostic biomarkers with AUC > 0.8 in two independent cohorts." (PMID 34944974, 2021). "PIK3R1 had lower expression in hepatocytes and medium expression in tumor cells." (PMID 33929972, 2021). "Among them, PIK3R1 has been reported to act as a tumor suppressor." (PMID 34745971, 2021). "Furthermore, two large-scale deletions in our dataset overlap known tumor suppressors, PIK3R1 and CUX1, and are likely drivers." (PMID 32697969, 2020). "Notably, two of the unclassifiable LGNET with high tumor content (uLGNET #1 and #2) had genetic signatures of RGNT with FGFR1 kinase domain hotspot missense mutation in combination with PIK3CA or PIK3R1 mutation." (PMID 32859279, 2020). "On the other hand, studies have demonstrated that PIK3R1 abrogation might reduce tumor proliferation and migration." (PMID 31402930, 2019). "There was enrichment for PIK3CA mutations in R258G tumours, and PIK3R1 in G356D (log2 odds ratios >2.5), however this failed to reach statistical significance." (PMID 31098401, 2019). "However, PIK3R1 usually is regarded as a tumour suppressor by serving as the regulatory subunit of PI3K." (PMID 31828111, 2019). "In our study, we proved that PIK3R1 expression was significantly increased in our six HCC cell lines, especially in HCCLM3 and MHCC97H cells, which exhibited the much higher metastatic ability, revealing that PIK3R1 may promote the tumor metastasis." (PMID 30497511, 2018). "To examine the effect of reduced PIK3R1 or R2 expression in lung SQCC tumor xenografts, we infected different cell lines with an inducible lentiviral vector that encodes a short hairpin specific for PIK3R1 or R2; stable clones expressed these shRNA after doxycycline induction." (PMID 27835880, 2016). "This was exemplified by Irs1 and Pik3r1 (p85) in PyMT tumours." (PMID 25200860, 2014).
tumor (continued). "Furthermore, deletion of PIK3R1 in mouse liver resulted in aggressive hepatocellular carcinomas with pulmonary metastasis, suggesting a tumor suppressor role." (PMID 22666248, 2012). "Similarly, LY294002 was utilized to determine whether the suchilactone/kaempferol combination exerts its role in immune activation and anti‐tumor activity by targeting PIK3R1." (PMID 38863309, 2024). "This suggests similarity in gene expression between each tumor which may reflect the shared mutational profile, including activating FGFR1 variants, in addition to PIK3R1 variants predicted to activate the PI3K signaling pathway, in concert with the germline PTPN11 variant." (PMID 39309743, 2024). "Interestingly, tumour‐induced alterations in the expression of Atrogin1, MuRF1, Pik3r1, Pdk4, Myh4, Myh2 and Myh1 were attenuated in EDA2R‐deficient muscles, implying that the EDA2R pathway contributes to the reprogramming of muscle gene expression during cancer cachexia." (PMID 39001644, 2024). "Therefore, PIK3R1/p85α, as a tumour suppressor, can maintain the stability of p110a of PI3K." (PMID 34741385, 2021). "Furthermore, PIK3R1 mutations destabilize PTEN, which is a key event leading to tumor development." (PMID 33159014, 2020). "Moreover, PIK3R1 is related to tumor size (P = 0.040) in clinical significance analysis." (PMID 31119098, 2019). "Moreover, there was a significantly inverse correlation between miR-486-5p and PIK3R1 expression levels in tumor tissue (r = −0.774, p < 0.01), it revealed that the expression of PIK3R1 might be affected by miR-486-5p in NSCLC." (PMID 31402930, 2019). "Furthermore, we observed that PIK3R1 (the regulatory subunit of PI3K) was inactivated in 6% of PDAC tumours; inactivated PIK3R1 promotes the phosphorylation of AKT, which itself promotes oncogenesis as it activates numerous OGs and inhibits TSGs within the cell." (PMID 30018740, 2018). "Somatic gain-of-function mutations in the coding region of both PI3K subunit genes, PIK3R1 (coding for p85α, the regulatory subunit of isoform α class I PI3K heterodimer) and PIK3CA (encoding the p110α catalytic subunit), are commonly found in many tumor types." (PMID 28143957, 2017). "Our studies show that the effects caused by abrogation of PIK3R1 and PIK3CA result from different signaling mechanisms in individual cell lines, likely reflecting different signaling mechanisms in the individual tumors (and perhaps in individual cells of the same tumor)." (PMID 22064833, 2011). "miR-486-5p has also been suggested to act as a tumor suppressor by targeting ARHGAP5 and PIK3R1, thereby facilitating NSCLC progression." (PMID 41451087, 2025). "In this study, we present novel insights that IGF2BP2 is essential for EGFR and PIK3R1 mRNA stability and activation of the EGFR/PI3K/AKT axis in OSCC tumor cells and CAFs." (PMID 40362183, 2025). "Other tumour driver genes (NF1, ATRX, PIK3R1, SPTA, and PIK3CA) marked by IntOGen,54 were also found among the top 12 mutated genes." (PMID 41292185, 2025). "An IHC assay indicated that PIK3R1 levels were decreased and γ-H2AX levels were increased, accompanied by tumor growth repression, after circPLPP4-ASO#1 application in the PDX-2 model." (PMID 38184597, 2024). "The most frequently mutated genes in human endometrial endometrioid cancer include the tumor suppressors PTEN and PIK3R1; the overwhelming majority of these cancers have abnormal activation of the PI3K/AKT signaling pathway." (PMID 37856394, 2023).
tumor (continued). "When down-regulated expression of PIK3R1 gene can inhibit PTEN function and reduce the degradation of PIP3 molecule, which was activated PI3K/AKT signaling to play the role of the tumor suppressor gene." (PMID 36688087, 2023). "Baseline PDX derived from P360 (BTY06) had overall low pTyr levels compared to the recurrent tumor (BTY29) that exhibited high phosphorylation of central regulator nodes, such as PIK3R1, STAT3, MAPK1, and MAPK3." (PMID 36077757, 2022). "Circ_0000215 is highly expressed in tumor tissues of NPC, and circ_0000215 contributes to malignant phenotypes of NPC through regulating miR-512-5p/PIK3R1 axis." (PMID 35545766, 2022). "We further used the GEPIA database to evaluate the expression differences of PIK3R1 and PIK3R2 between the tumor and the control tissues as the corresponding control data was not available in the TIMER database for some tumors." (PMID 35395865, 2022). "The SPINK1 general cancer pathway and HGF signalling were activated in G3 cells in which the tumour malignancy‐related genes RASD1, PIK3R1, JUN, and FOS were significantly upregulated, indicating that G3 promotes malignant progression in GC." (PMID 35184420, 2022). "PIK3R1 is the predominant regulatory isoform of PI3K, a tumor-suppressor gene in OSCC, regulating cancer cell proliferation." (PMID 34335829, 2021). "We analyzed the effect of driver gene expression in the different subtypes and found that the expression of PIK3CA, PIK3R1, and PTEN was significantly lower in tumor samples than in normal samples." (PMID 34277633, 2021). "PIK3R1 is a critical component of the PI3K/AKT signaling pathway, deregulation of the phosphoinositide 3-kinase (PI3K) pathway contributes to tumor development and progression." (PMID 34490085, 2021). "It has been reported that both PTEN and PIK3R1 (also known as PI3K p85α), a regulatory subunit of PI3K, are capable of inactivating the PI3K/AKT signaling and inhibiting tumor progression." (PMID 34141708, 2021). "PIK3R1 and VAV1 are known oncogenes, SYK is a tumor suppressor gene, and PTPN6 has a tumor suppressor role." (PMID 32293263, 2020). "In addition, PIK3R1 may function as tumor suppressor in LSCC by promoting cell growth." (PMID 31938022, 2020). "Given the tumor suppressor functions and overlapping mechanisms of action of SOCS1, SOCS3 and PIK3R1, further work is needed to disentangle the highly significant negative correlation between SOCS1/SOCS3 and PIK3R1." (PMID 32807134, 2020). "PIK3R1 is indeed a pivotal kinase negatively regulating the catalytic subunit (PIK3CA) of the PI3K complex and antagonized by the tumor suppressor PTEN." (PMID 32321919, 2020). "Another ASC-probe (#3) derived from a tumor-containing lymph node reacted strongly with a ~80 kDa protein in the soluble MCF-7 extract, and with the product of the PIK3R1 gene on the microarray." (PMID 31100936, 2019). "We used IHC methods to determine LIFR, PIK3R1, and MMP12 protein expression in 20 GBC tumor tissues and patient-matched adjacent peritumor tissues." (PMID 31119098, 2019). "Our results further support the tumour suppressing role of miR-221 in PCa, since it sensitises PCa cells towards TRAIL by regulating the expression of the oncogenes SOCS3 and PIK3R1." (PMID 31828111, 2019). "As a tumor suppressor, FOXA1 targets PIK3R1 directly to inhibit PI3K/Akt signaling pathway, thus exerting a negative regulatory effect on proliferation, migration, and invasion of HCC in male patients." (PMID 29208003, 2017). "To analyze the status of PI3K pathway in shRNA-treated tumors, we tested extracts from control, PIK3R1 and PIK3R2 shRNA-treated-H226, -CaLu-1 and -H520 tumor samples." (PMID 27835880, 2016).